SYNPR (synaptoporin)
Description:
Intrinsic membrane protein of small synaptic vesicles. Probable vesicular channel protein (By similarity).
Synonyms: MGC26651; SPO
Tractability: Antibody: UniProt predicts a signal peptide or a membrane-spanning region. PROTAC: ubiquitination databases record sites on it; its protein half-life has been measured.
Gene: Protein-coding gene on chromosome 3 (63,228,315 to 63,616,924, forward strand). Ensembl gene ENSG00000163630.
Subcellular location: Cytoplasmic vesicle, secretory vesicle, synaptic vesicle membrane; Synapse, synaptosome
Subcellular location (Human Protein Atlas): Vesicles; Cytosol; Nucleoplasm
Gene Ontology:
Molecular function: protein binding
Cellular component: synaptic vesicle membrane; membrane; synapse; synaptic vesicle
Genetic constraint (gnomAD): Loss-of-function variants: 23 observed, 32.63 expected, observed/expected ratio (o/e) 0.7, 90% interval 0.51 to 1. The upper end of that interval is the gene's LOEUF score, 1, which puts it in group 4 of 6, group 1 being the genes least tolerant of losing a copy. Missense variants: 318 observed, 358.14 expected, observed/expected ratio (o/e) 0.89, 90% interval 0.81 to 0.97. Synonymous variants: 146 observed, 140.03 expected, observed/expected ratio (o/e) 1.04, 90% interval 0.91 to 1.2.
Homologues: Orthologues: chimpanzee SYNPR (99% identical), macaque SYNPR (99% identical), dog SYNPR (97% identical), rat Synpr (96% identical), rabbit SYNPR (96% identical), mouse Synpr (95% identical), guinea pig SYNPR (95% identical), pig SYNPR (90% identical), tropical clawed frog synpr (78% identical), zebrafish synpra (67% identical), Caenorhabditis elegans sph-1 (24% identical). Paralogues in human: SYP (61% identical), SYPL2 (43% identical), SYPL1 (39% identical).
Diseases named in the same sentence as SYNPR in open-access papers:
SYNPR is named in the same sentence as 7 diseases in open-access papers, as found by Europe PMC text mining. Sharing a sentence is not in itself a finding about the gene and the disease. The quoted sentences say what the papers report.
Anxiety (1 paper, 2020). Intense feelings of nervousness, tension, or panic often arise in response to interpersonal stresses. "In the present study, Reelin injection into the hippocampus reversed impairments in object recognition memory and anxiety-like behavior, as well as the decreased in synaptoporin-immunoreactive area in the hippocampus, in an MIA animal model of schizophrenia." (PMID 32982694, 2020). "Microinjections of recombinant Reelin protein into the hippocampus rescued impairments in object memory and anxiety-like behavior and recruited synaptoporin in the hippocampus in offspring exposed to antenatal inflammation." (PMID 32982694, 2020).
schizophrenia (1 paper, 2020). A major psychotic disorder characterized by abnormalities in the perception or expression of reality. "Patients with schizophrenia have both decreased synaptoporin levels and mossy fiber deficits, indicating that synaptoporin expression may be a good marker for hippocampal synaptic disturbances in schizophrenia." (PMID 32982694, 2020).
Sepsis (1 paper, 2025). Sepsis is defined as life-threatening organ dysfunction caused by a dysregulated host response to infection. "The determination of key genes, such as PRIM2, SYNPR, and RBSN, through pre-operative blood tests could enhance risk stratification, enable early detection of post-operative sepsis, and guide targeted interventions to improve patient outcomes." (PMID 41473159, 2025).
tumor (4 papers, 2022 to 2024). "Shared decreased protein-coding genes across all tumor types included FOXP2, GABRA1/2/4/5, NRGN, SST, and SYNPR." (PMID 36865335, 2023).
SYNPR also shares sentences with these, for which no sentence is quoted: lymph node metastasis (1 paper); mammary tumour (1); migraine (1).